EBF1 (EBF transcription factor 1)
Diseases named in the same sentence as EBF1 in open-access papers (continued):
Sharing a sentence is not in itself a finding about the gene and the disease.
coronary artery disease (6 papers, 2018 to 2024). "EBF1 is a transcription factor with the hematopoietic function that has been associated with early onset coronary artery disease." (PMID 35886043, 2022). "Another study out of China demonstrated that two SNPs in EBF1 contribute to the risk of Coronary Artery Disease, especially in patients who drink or smoke." (PMID 33732506, 2021). "The present study analyzes the influence of EBF1 gene polymorphism and its interaction with smoking and drinking on the risk of coronary artery disease (CAD)." (PMID 29789399, 2018). "Genome-wide association studies (GWAS) have linked EBF1 to multiple human cardiovascular disorders, including coronary heart disease 19-22, cardiovascular metabolic disease 23 and orthostatic hypotension 24, implying its potential roles in the human cardiac system." (PMID 39239522, 2024). "Recent systems biology and genome-wide association studies link EBF1 to various human cardiovascular diseases, such as coronary heart disease 19-22, cardiovascular metabolic disease 23 and orthostatic hypotension 24, implying its potential roles in the human cardiac system." (PMID 39239522, 2024). "Several unbiased Genome-Wide Association Studies (GWAS) or targeted correlative studies have uncovered strong associations of numerous Single Nucleotide Polymorphisms (SNPs) in EBF1 with metabolic traits or diseases, including waist circumference, BMI, Coronary Heart Disease, and blood pressure." (PMID 33732506, 2021). "In our study, we found four genes with single nucleotide variants (SNVs) associated with coronary artery disease—HNF1A, LOX, SMAD3, and SMARCA4, and one gene, EBF1, with a SNV associated with carotid intima media thickness for the gens in significant modules." (PMID 35925965, 2022).
Hypertension (6 papers, 2012 to 2025). The presence of chronic increased pressure in the systemic arterial system. "Furthermore, the EBF1 locus is implicated in the regulation of blood pressure, suggesting another possible link between PTB and hypertension." (PMID 36553520, 2022). "However, none of these SNPs overlap with significant SNPs in our results, with the exception of two studies of hypertension/systolic blood pressure, each of which reported one significant association with a SNP in EBF1; unfortunately, neither of those two SNPs was examined in our study." (PMID 22369142, 2012). "A variety of statistically significant genetic polymorphisms were identified that can be attributed to the heritability of varicose veins affecting inflammation and immunity (eg, PPP3R1, EBF1, and GATA2), hypertension (eg, CASZ1), and vascular architecture (eg, CASZ1, PIEZO1, and STIM2)." (PMID 41391741, 2025). "However, Ebf1 function has not been previously assessed in the context of cardiovascular disease, hypertension, or neuroinflammation." (PMID 28732007, 2017).
cholangiocarcinoma (5 papers, 2018 to 2025). A carcinoma that arises from the intrahepatic biliary tree (intrahepatic cholangiocarcinoma) or from the junction, or adjacent to the junction, of the right and left hepatic ducts (hilar cholangiocarcinoma). "We have previously reported that early B cell factor 1 (EBF1) was down-regulated in cholangiocarcinoma (CCA) tissues and related to tumor progression." (PMID 33854627, 2021). "Recently, we found downregulation of early B cell factor 1 (EBF1), a tumor suppressor gene, in cholangiocarcinoma-cultured cells and ox-MMNK1-L cells compared to normal cholangiocyte cells (MMNK1)." (PMID 30340457, 2018). "Cholangiocarcinoma patients with low EBF1 expression and high formation of 8-oxodG had poor survival." (PMID 30340457, 2018). "EBF1 downregulation was also found in OV-related cholangiocarcinoma tissues." (PMID 30340457, 2018). "Thus, prolonged oxidative stress due to chronic inflammation may suppress EBF1 function, leading to cholangiocarcinoma genesis via stem cell DNA damage." (PMID 30340457, 2018). "In cholangiocarcinoma (CCA), EBF1 expression is suppressed by promoter hypermethylation and chronic oxidative stress exposure." (PMID 40508012, 2025).
lymphoma (5 papers, 2004 to 2024). A malignant (clonal) proliferation of B- lymphocytes or T- lymphocytes which involves the lymph nodes, bone marrow and/or extranodal sites. "For example, Ebf1 that is an important regulator for B cell fate and IgHa that has a potential role in lymphoma development changed the compartment states from inactive B compartment in ES cells to active A compartment both in pro-B cell and lymphoma with increased gene expression changes." (PMID 30894186, 2019). "For instance, B-cell eCGIs are enriched for regions binding key TFs involved in B-lymphopoiesis and lymphoma pathogenesis (such as BCL11A, EBF1, IKZF1 and SPI1), whereas ESC-specific eCGIs are enriched for binding of NANOG, a key TF regulating pluripotency." (PMID 26512062, 2016). "Since EBF1, PAX5, and MYC are essential for B cell development, their ectopic expression or mutants may lead to abnormal B cell development and hematologic neoplasms, such as B-lymphoid leukemia and lymphoma." (PMID 38318177, 2024). "Finally, co-IP after cross-linking using a human lymphoma B cell line (BJAB) and an Abelson Murine Leukemia Virus (AMuLV)-transformed B cell line (pre-B) further show that MEF2C and EBF1 may exist in the same complex." (PMID 26900922, 2016).
prostate carcinoma (5 papers, 2017 to 2025). A carcinoma that arises from epithelial cells of the prostate gland. "EBF1, or early B cell factor 1, has been implicated in the development of prostate cancer through its regulation of androgen receptor (AR) signaling and the androgen response." (PMID 39364872, 2025). "NR2F2 (COUP-TFII) plays a critical role in mediating the effects of DHA treatment on EFNB2, EBF1, ETS1, and VEGFA expression, and the knockdown of NR2F2 can recede the functional changes induced by DHA treatment in prostate cancer cells." (PMID 39364872, 2025).
B cell lymphomas (4 papers, 2018 to 2024). "Moreover, a recent study showed that EBF1 is necessary for propagating mantle cell lymphoma, a lethal mature B cell lymphoma." (PMID 38318177, 2024). "Therefore, EBF1, PAX5, and MYC lesions may drive B-cell malignancy and induce B-cell lymphomas." (PMID 38318177, 2024).
bladder cancer (4 papers, 2022 to 2024). "TMPO-AS1 has been implicated in several cancers, is activated by EBF1 and also indirectly activates EBF1 by sponging the microRNA miR-98-5p in bladder cancer." (PMID 38838009, 2024). "A feedback loop involving TMPO-AS1/miR-98-5p/EBF1, which significantly impacts the development of bladder cancer, was demonstrated; in this loop, TMPO-AS1 is sponged by miR-98-5p, which subsequently targets EBF1." (PMID 38872210, 2024). "Additionally, TMPO-AS1 regulates bladder cancer progression via the TMPO-AS1/miR-98-5p/EBF1 signaling axis." (PMID 35685867, 2022). "This study is to elucidate the effect of the LINC00663/EBF1/NR2F1 axis on inflammation and angiogenesis in bladder cancer (BC) and related molecular mechanisms." (PMID 39219375, 2024).
glioma (4 papers, 2020 to 2025). A benign or malignant brain and spinal cord tumor that arises from glial cells (astrocytes, oligodendrocytes, ependymal cells). "Compared with NBTs, the protein level of EBF1 in glioma tissues was observed to be relatively lower, with a further decline evident at higher pathological grades." (PMID 39794701, 2025). "HIF1α in TNBC and NR2F2 in PCa enhance EBF1 expression, while ZNF521 in GC and Sox2 in glioma act as negative regulators, indicating that EBF1 functions as a central node at the convergence of multiple signaling pathways." (PMID 40508012, 2025). "In glioma stem cells (GSCs), EBF1 expression is inversely correlated with Sox2." (PMID 40508012, 2025). "According to our observations, in the same manuscript, the authors also identified EBF1 as a significantly upregulated gene in microdissected glioma vessels surrounding palisading cells, a typical feature of glioblastoma where angiogenesis is particularly active." (PMID 34272603, 2021). "TET2, as an interaction partner of the transcription factor EBF1, regulates DNA methylation in gliomas 44, STAT5b also could recruit TET2 in specific site to promote DNA demethylation." (PMID 32194873, 2020). "In line with the glioma tissues, the GBM cells, such as U251 and U373, also exhibited significantly reduced EBF1 expression compared with NHAs." (PMID 39794701, 2025). "In vivo, EBF1 overexpression markedly reduced GSC tumorigenicity, indicating its potential as a key regulator of glioma differentiation." (PMID 40508012, 2025).
thyroid cancer (4 papers, 2021 to 2025). "It functions as a tumor suppressor in thyroid cancer by negatively regulating EBF1 (Early B cell factor 1), which has a partial role in the inhibition of tumor growth and metastasis, and its downregulation is associated with advanced disease and poor prognosis." (PMID 40136629, 2025). "EBF1 was proved to be a target of LINC00261, and EBF1 overexpression could reverse the inhibition of LINC00261 on the proliferative and migration of thyroid cancer cells." (PMID 39219375, 2024).
triple-negative breast carcinoma (4 papers, 2023 to 2025). An invasive breast carcinoma which is negative for expression of estrogen receptor (ER), progesterone receptor (PR), and human epidermal growth factor receptor 2 (HER2). "EBF1 is a tumor-promoting TF in triple-negative breast cancer, whereas SNAI1/2 are master regulatory TFs for organogenesis and wound healing in normal tissue as well as for the epithelial–mesenchymal transition (EMT) in cancer cells." (PMID 37234983, 2023). "Finally, amongst the highlighted genes was Ebf1 transcription factor and oncogene that is shown to assemble a transcriptional complex with Hif1a to suppress p300 activity in triple negative breast cancer and is included in the neural crest gene regulatory network." (PMID 41446274, 2025).
B-cell acute lymphoblastic leukemia (3 papers, 2020 to 2025). A neoplasm of lymphoblasts committed to the B-cell lineage, typically composed of small to medium-sized blast cells. "EBF1 functions as a transcription factor, which, in conjunction with PAX5, significantly regulates the developmental process of normal and malignant B-cell acute lymphoblastic leukemia by binding to MYC gene regulatory elements." (PMID 39794701, 2025).
Burkitt lymphoma (3 papers, 2020 to 2022). A rare form of malignant mature B-cell non-Hodgkin lymphoma. "We find that EBV episomes in Burkitt’s lymphoma cells preferentially associate with cellular genomic sites containing EBNA1 binding sites enriched with B-cell factors EBF1 and RBP-jK, the repressive histone mark H3K9me3, and AT-rich flanking sequence." (PMID 32054837, 2020). "One report demonstrates that the co-localization of viral protein EBNA2, and B-cell-specific transcription factor EBF1 at the miR-34a promoter, leads to the repression of miR-34a, which targets the PDl1 3′UTR in Burkitt lymphoma (BL) and Diffuse Large B-Cell Lymphoma (DLBCL) cells." (PMID 32722019, 2020).
diffuse large B-cell lymphoma (3 papers, 2020 to 2023). "We used the KIS-1 diffuse large B cell lymphoma cell line, which is reported to have elevated levels of PAX5 expression, to investigate the mechanism of EBF1- and PAX5-regulated gene expression." (PMID 33452395, 2021).
lipodystrophy (3 papers, 2017 to 2023). A congenital or acquired disorder characterized by abnormal loss or redistribution of the adipose tissue in the body. "The subsequent observation that global Ebf1−/− mice present with severe lipodystrophy, in addition to stunted growth and runting, confirms a crucial role for Ebf1in adipogenesis." (PMID 37887382, 2023). "Ebf1−/− mice also present significantly reduced circulating leptin levels, consistent with lipodystrophy, and increased food intake." (PMID 37887382, 2023). "Studies in knockout mice have revealed a function for EBF1 in metabolism due to mouse phenotypes including lipodystrophy, hypotriglyceridemia, and hypoglycemia." (PMID 28183271, 2017). "Compared with the wild type controls, the symptom of lipodystrophy in the EBF1 knockout mice is characterized by additional brown adipose tissue and a striking reduction in white adipose tissue in the bone marrow." (PMID 28183271, 2017). "Moreover, inconspicuous lipodystrophy, hypotriglyceridemia, and hypoglycemia have also been identified in EBF1 knockout mice." (PMID 28183271, 2017). "We have developed a Fat-Specific Ebf1 Knockout (FEBKO) animal model (genotype Ebf1fl/fl, Ad-Cre+, equivalent to the Ebf1ΔAdipoq animals discussed earlier), which circumvents the confounding issues of lipodystrophy as well as global Ebf1 heterozygosity (a limitation of the Gao paper, in my opinion)." (PMID 33732506, 2021).
lupus (3 papers, 2015 to 2021). "In our studies, we found that elevation of the expression level of miR-1246 in lupus B cells could decrease the expression of EBF1 causing the downregulation of CD40, CD80, and CD86 which are co-stimulatory molecules required for full B cell activation and IgG secretion." (PMID 25789080, 2015).
multiple sclerosis (3 papers, 2005 to 2023). A progressive autoimmune disorder affecting the central nervous system resulting in demyelination. "Allele and genotype frequencies of the EBF1 polymorphism in multiple sclerosis patients and controls." (PMID 16255771, 2005). "The role of the EBF1 gene in multiple sclerosis susceptibility was analyzed by performing a case-control study with 356 multiple sclerosis patients and 540 ethnically matched controls comparing the EBF1 polymorphism rs1368297 and the microsatellite D5S2038." (PMID 16255771, 2005). "EBF1 is involved in Schwann cell myelination and axonal pathfinding (such proteins are often similarly used for OPC migration) and specific polymorphisms of this gene increase risk of multiple sclerosis, suggesting that it may be important to better understand its function in OPCs." (PMID 37217978, 2023). "Furthermore, Ebf1 may exert a role in the pathophysiology of multiple sclerosis." (PMID 28732007, 2017). "Genotype frequencies of the EBF1 polymorphism in HLA-DRB1*1501 positive and negative multiple sclerosis patients." (PMID 16255771, 2005).
acute myeloid leukemia (2 papers, 2011 to 2021). Acute myeloid leukemia (AML) is a group of neoplasms arising from precursor cells committed to the myeloid cell-line differentiation. "Concordantly, several TF were reported to interact with TET2, including Wilms Tumor 1 (WT1), which was found to recruit TET2 to its target genes in acute myeloid leukemia (AML) cells, or early B-cell factor 1 (EBF1), which was reported to interact with TET2 in IDH-mutant cancers." (PMID 33692344, 2021).
anorexia nervosa (2 papers, 2021 to 2023). A disorder most often seen in adolescent females characterized by a refusal to maintain a minimally normal body weight, an intense fear of gaining weight, a disturbance in body image, and, in postmenarcheal females, the development of amenorrhea. "What makes the Ebf1−/− bone phenotype so interesting is the fact that a majority of human patients with anorexia nervosa (at least in one genome-wide association study of 700 females of European descent) have SNPs in EBF1 and also have elevated levels of bone marrow adiposity and low leptin levels." (PMID 37887382, 2023).
Anxiety (2 papers, 2025). Intense feelings of nervousness, tension, or panic often arise in response to interpersonal stresses. "Together, our transcriptional analysis suggests that at least two, molecularly distinguishable, LepRLH subpopulations have dissociable roles in the adaptive regulation of anxiety behavior, whereby Ebf1 expression in LepR subpopulation may be associated with reduced anxiety." (PMID 41116115, 2025). "Here we found that high-anxiety animals were characterized by lower coexpression of Ebf1 in LepRLH neurons." (PMID 41116115, 2025). "Low-anxiety animals as tested in the EPM tended to have larger LepR+ Ebf1+ populations." (PMID 41116115, 2025). "To test whether Ebf1 coexpression with LepR in LH neurons is relevant for anxiety behavior, we transfected LepRLH neurons with mCherry, measured anxiety behavior in both the EPM and the OF test and costained LepRLH neurons for Ebf1." (PMID 41116115, 2025). "We observed a similar negative correlation between LepR+Ebf1+ coexpression (assessed using multilabeling in situ hybridization) and anxiety as tested in the EPM." (PMID 41116115, 2025).
atherosclerosis (2 papers, 2017 to 2018). A disease characterized by the build-up of fatty material and calcium deposition in the arterial wall resulting in partial or complete occlusion of the arterial lumen. "This evidence suggests that EBF1 may be associated with atherosclerosis, and there is evidence that EBF1 is a risk factor for CAD." (PMID 29789399, 2018). "The EBF1 gene has also been identified as potential critical regulatory gene for the formation of atherosclerosis and CAD." (PMID 28183271, 2017). "Meanwhile, many EBF1 target genes have been associated with intima-media thickness (IMT) of carotid artery, a marker of subclinical atherosclerosis with high heritability." (PMID 28183271, 2017).
autism (2 papers, 2019 to 2020). Persistent deficits in social interaction and communication and interaction as well as a markedly restricted repertoire of activity and interest as well as repetitive patterns of behavior. "Common genetic variations in EBF1 have also been associated with premature birth and autism." (PMID 32912160, 2020). "Genetic variants in EBF1 could potentially contribute to low baseline cardiac vagal parasympathetic activity observed in prematurity and autism." (PMID 30109601, 2019). "EBF1 is involved in regulation of cell differentiation in the murine striatum; mutation in this gene could likely contribute to the striatal abnormalities observed in autism." (PMID 30109601, 2019). "Thus, abnormal expression of EBF1 gene could disrupt the MGVHB by affecting the gut, vagus nerve, the heart, and the brain in prematurity and autism." (PMID 30109601, 2019).
autoimmune disease (2 papers, 2005 to 2017). A disorder resulting from loss of function or tissue destruction of an organ or multiple organs, arising from humoral or cellular immune responses of the individual to their own tissue constituents. "The EBF prototypical regulatory activity in B lymphocyte differentiation alone justifies the functional involvement of the EBF1 gene in an autoimmune disease as MS." (PMID 16255771, 2005).
B cell deficiency (2 papers, 2022). A broad classification of disorders where circulating numbers of B lymphocytes are decreased or ineffective. "To disentangle the effects of Ebf1 deletion in HSPCs from the effects of B cell deficiency, we analyzed B cell–deficient IghmTm1 mice, also known as muMT− mice, which lack the expression of membrane-bound IgM." (PMID 36048017, 2022).
chronic lymphocytic leukemia (2 papers, 2021 to 2024). "Furthermore, the early compartmental switch (A to I) of the EBF1 factor in B cells of patients with chronic lymphocytic leukemia results in the loss of chromatin interactions, and therefore, the downregulation of EBF1 has become a diagnostic marker for chronic lymphocytic leukemia." (PMID 38586584, 2024). "Recently, a key contributor to B-cell lymphopoiesis, Early B cell factor 1 (EBF1), has been shown to possess an inhibitory role in chronic lymphocytic leukemia (CLL) through inactivation of the STAT5 pathway." (PMID 34055801, 2021).